SOCS4 (suppressor of cytokine signaling 4)
Diseases named in the same sentence as SOCS4 in open-access papers (continued):
Sharing a sentence is not in itself a finding about the gene and the disease.
cancer (10 papers, 2015 to 2025). A tumor composed of atypical neoplastic, often pleomorphic cells that invade other tissues. "In contrast, miR-944 promotes the corresponding cancer cell proliferation by targeting three genes (SOCS4, CADM2, and HECW2) and participating in the LINC00899/miR-944/ESR1signaling axis." (PMID 36077769, 2022). "The SOCS4 levels were dramatically reduced within ESCC tissues compared to the adjacent non-carcinoma samples." (PMID 35619921, 2022). "For example, in epithelial cancer cells, the Runx1 transcription factor promotes cancer cell growth via direct repression of SOCS4 and subsequent activation of STAT3." (PMID 34439155, 2021). "Tumbar and the colleagues reported that transcriptional repression of SOCS3 and SOCS4 by RUNX1 were essential for cancer cell growth in oral, skin, and ovarian epithelial human cancer cells." (PMID 28750679, 2017). "Moreover, SOCS4 restoration regulated the expression of downstream cancer stemness and proliferation genes." (PMID 40140827, 2025). "Moreover, miR-106b-5p and miR-93-5p affected the SOCS4 levels, inducing a decrease of SOCS4 and reversing the functions of miR-106b-5p and miR-93-5p in cancer progression." (PMID 35619921, 2022). "Accumulating evidence suggests that SOCS4 plays a role in the pathobiology of several cancers." (PMID 34439155, 2021). "Furthermore, let-7 participates in the JAK2/STAT signaling pathway in cancer cells by targeting SOCS4 and activates the JAK1/STAT3 signaling pathway." (PMID 34568312, 2021). "Currently, two reports have implied the potential role of SOCS4 in cancer." (PMID 26437444, 2015). "In this study, we identified a novel miR-876/SOCS4/STAT3/PD-L1 regulatory axis in oral cancer, which promotes cancer stemness and progression, ultimately leading to recurrence and poor prognosis." (PMID 40140827, 2025). "In LUSC, miR-944 targets and inhibits SOCS4, which in turn activates the Jak/STAT signaling pathway and promotes the growth and proliferation of cancer cells." (PMID 36077769, 2022). "Moreover, the inhibitory effects of anti-miR-500a-3p on cancer stem cell phenotypes and activity of STAT3 signaling were reversed by silencing SOCS2, SOCS4 and PTPN11 in miR-500a-3p-downexpressing cells, respectively." (PMID 28750679, 2017). "Our findings further reveal miR-500a-3p promotes the cancer stem cell characteristics via targeting multiple negative regulators of JAK/STAT3 signaling pathway, including SOCS2, SOCS4 and PTPN11, leading to constitutive activation of STAT3 signaling." (PMID 28750679, 2017).
infection (6 papers, 2014 to 2024). The state of being infected such as from the introduction of a foreign agent such as serum, vaccine, antigenic substance or organism. "This is the first description of SOCS4-deficient mice and suggests that SOCS4 will play an important role in immune regulation during infection." (PMID 24809749, 2014). "The gene encoding SOCS4 has been shown to be widely expressed, and induced by epidermal growth factor (EGF), while infection can indirectly increase SOCS4 protein levels." (PMID 35204004, 2022). "Socs5 mRNA was expressed in uninfected mouse lungs and was significantly upregulated at day two post-infection; by comparison, Socs4 was expressed at very low levels even during infection." (PMID 28195529, 2017). "Socs4 mRNA expression increased over time, peaking at day 3 post-infection (due either to the changing cellular composition or to up-regulation within the infiltrating cells)." (PMID 24809749, 2014). "Studies were done using SOCS4KO mice and results demonstrated that lacking SOCS4 resulted in rapid infection with a H1N1 influenza as well as being more susceptible to other pathogenic infections." (PMID 39676878, 2024). "Although, virus-specific cells did not traffic efficiently to the site of infection, the clearance of virus on day 7 post-infection indicates that the loss of SOCS4 does not affect the ability of CD8 T cells to kill the virus." (PMID 24809749, 2014). "We also observed that the genes involved in fundamental cellular processes such as SOCS4, AKT, NOTCH and WNT) were also upregulated in the early stages of infection." (PMID 36851710, 2023). "We demonstrate that mice lacking functional SOCS4 protein rapidly succumb to infection with a pathogenic H1N1 influenza virus (PR8) and are hypersusceptible to infection with the less virulent H3N2 (X31) strain." (PMID 24809749, 2014). "We demonstrate that mice lacking SOCS4 rapidly succumb to infection with a pathogenic H1N1 influenza virus and are hypersusceptible to infection with the less virulent H3N2 strain." (PMID 24809749, 2014). "Following infection with a viral strain of relatively moderate virulence, the absence of a functional SOCS4 protein led to dysregulated cytokine production akin to a cytokine storm." (PMID 24809749, 2014).
SOCS4 also shares sentences with these, for which no sentence is quoted: lung squamous cell cancer (2 papers); asthma (1); endometrial carcinoma (1); esophageal squamous cell carcinoma (1); Lymphatic Metastasis (1); ovarian carcinoma (1); parasite infection (1); renal carcinoma (1); thalassemia (1).